BRAF (B-Raf proto-oncogene, serine/threonine kinase)
Diseases named in the same sentence as BRAF in open-access papers (continued):
Sharing a sentence is not in itself a finding about the gene and the disease.
thyroid cancer (continued). "Based on these considerations, this study aimed to investigate a customized multigene panel for detecting mutations in thyroid cancer oncogenic drivers (BRAF, KRAS, NRAS, EGFR, and PI3KCA) and correlate the obtained results with clinical and pathological characteristics of the affected patients." (PMID 39420942, 2024). "BRAF inhibitors are mostly utilized in thyroid cancer patients with the BRAF V600E mutation." (PMID 38501105, 2024). "Additionally, long-term survival studies are needed to clarify further the impact of the BRAF mutation and biomarker dynamics on thyroid cancer prognosis." (PMID 39767732, 2024). "Similarly, TG and BRAF V600E mutation analyses help delineate subtype-specific prognostic implications, contributing to a broader understanding of thyroid cancer pathophysiology." (PMID 39767732, 2024). "In conclusion, mutations in thyroid cancer associated with BRAF inhibitor resistance may also be associated with thyroid tumor dedifferentiation." (PMID 38275291, 2024). "However, the mechanism underlying the resistance of BRAF-mutant thyroid cancers to its specific inhibitors is far more complex than we thought." (PMID 38795180, 2024). "Notably, the BRAF^V600E mutation has been shown to induce PD-L1 expression, making it a viable immunotherapeutic target in thyroid cancer." (PMID 38403820, 2024). "Previous research results indicate that thyroid cancer with intraglandular dissemination has a higher likelihood of lymph node metastasis, higher rates of capsule invasion, higher rates of vascular invasion, and a greater likelihood of BRAF V600E mutation." (PMID 39135992, 2024). "TERT promoter mutation often co-exists with BRAF or RAS mutation in thyroid cancer." (PMID 39235852, 2024). "This indicates that the BRAF mutation is associated with greater tumor aggressiveness, consistent with the existing literature that highlights its link to more aggressive clinicopathological features of thyroid cancer." (PMID 39767732, 2024). "However, in general, the presence of BRAF V600E has been associated from around 18 to 87% of thyroid cancers." (PMID 38539548, 2024). "Although BRAF mutation is the most common mutation in thyroid cancer, analyzing only the BRAF mutation status to determine tumor origin may lead to an increased positivity rate for intraglandular dissemination." (PMID 39135992, 2024). "It is reported that RAS mutations may occur later than BRAF mutations and correlate with aggressive disease progression of BRAF-mutant thyroid cancers." (PMID 37622214, 2024). "Thus, there is an urgent need to explore the mechanisms underlying the resistance to BRAF inhibitors in BRAF-mutant thyroid cancers and develop effective strategies to improve their sensitivity to BRAF inhibitors." (PMID 38795180, 2024). "The differential effects of formalin fixation on DNA and RNA quality present a challenge in optimizing sample preparation for thyroid cancer genomic analysis, where both DNA-based (e.g., BRAF V600E mutations) and RNA-based (e.g., RET and NTRK fusion genes) analyses are crucial." (PMID 39560912, 2024). "This specific BRAF mutation is rarely found in eutopic thyroid gland carcinomas." (PMID 38396644, 2024). "Likewise, phase II clinical trials have demonstrated noteworthy response rates in advanced BRAF-mutated thyroid carcinomas when treated with a combination of the BRAF inhibitor dabrafenib and MEK inhibitor trametinib." (PMID 37985676, 2024).
thyroid cancer (continued). "However, to our knowledge, no study has shown the differences in TNFRSF1B (encoding TNFR2) methylation (and thereby expression of TNFR2) dependent on BRAF mutation status in thyroid cancer." (PMID 36975440, 2023). "This mutation is the most frequently found in thyroid cancers, accounting for more than 90% of oncogenic BRAF mutations, and drives thyroid tumorigenesis and progression by activating the mitogen-activated protein kinase/extracellular signal-regulated protein kinase (MAPK/ERK) signaling pathway." (PMID 36834830, 2023). "Further experiments found that DSF/Cu sensitizes BRAF-mutated thyroid cancer cells to PLX4032 by suppressing the reactivation of HER3 caused by PLX4032, thereby blocking MAPK and PI3K/AKT pathways, and NAC could reverse this effect." (PMID 36834830, 2023). "In addition, in the presence of the most common BRAF mutation in thyroid cancer, the expression of SRPX2 was significantly higher than that in WT group." (PMID 37306872, 2023). "BRAF (v‐raf murine sarcoma viral oncogene homologue B1) mutation is the most frequent gene mutation responsible for the development of thyroid cancer and induces invasion of thyroid cancer." (PMID 37246589, 2023). "Moreover, another study showed that the induction of ROS production and decreasing antioxidant barrier of thyroid cancer cells by vitamin C selectively occurred in BRAF‐mutated cells." (PMID 37246589, 2023). "The BRAF V600E mutation is common in thyroid cancer, as is DNA methylation." (PMID 36975440, 2023). "Environmental and genetic factors play important roles in the pathogenesis of thyroid cancer, and genetic changes, such as BRAF and RAS mutations or RET/PTC rearrangement leading to activation of the oncogenic MAPK pathway, are closely related to the occurrence of thyroid cancer." (PMID 36791151, 2023). "However, the mechanisms causing adaptive resistance to BRAF inhibitors in thyroid cancer remain to be elucidated, and strategies to overcome drug resistance are urgently needed in clinical practice." (PMID 37325052, 2023). "By comparing the two figures, it could be seen that the mutation frequency of each gene in the high and low-rating groups was usually different, and the mutation frequency of the thyroid cancer tumor marker BRAF gene was higher in the low-rating group." (PMID 36791151, 2023). "TERTp mutations, a high number of somatic mutations and subclonal BRAF mutations may correlate with worse clinical features and should be considered in the risk stratification of thyroid cancer." (PMID 37465126, 2023). "Although BRAF mutation is a driver mutation in thyroid cancer, its clonality varies." (PMID 37465126, 2023). "In summary, by a series of in vitro and in vivo studies, we demonstrated that DSF/Cu kills BRAFV600E-mutated thyroid cancer cells and improved their response to BRAF kinase inhibitors through relieving the feedback activation of MAPK/ERK and PI3K/AKT pathways in an ROS-dependent way." (PMID 36834830, 2023). "Our results are reinforced by other studies that have reported that BRAF mutations are associated with higher expression of the PD-L1 protein in thyroid cancer, and that increased PD-L1 expression is significantly associated with disease recurrence and poor survival." (PMID 37373171, 2023). "Specifically, there are diagnoses of specific diseases by traditional and deep learning, such as diagnosis of hepatocellular carcinoma (HCC), triple negative breast cancer, cervical tuberculous lymphadenitis, and v-raf murine sarcoma viral oncogene homolog B (BRAF) mutation in thyroid cancer." (PMID 37828411, 2023). "The BRAF mutation rates for thyroid cancer were high (63%, n = 11/16)." (PMID 36251535, 2023). "Our result is consistent with previous studies on BRAF mutation and thyroid cancer." (PMID 36975440, 2023). "The BRAF V600E mutation is responsible for a large percentage of thyroid cancer." (PMID 36251535, 2023).
thyroid cancer (continued). "Similarly, panobinostat in combination with MAPK and the BRAF inhibitor dabrafenib has shown synergistic antitumor effects in BRAF-mutated thyroid carcinoma cells." (PMID 38258065, 2023). "Patients with BRAF mutation had significantly higher risk thyroid carcinomas." (PMID 37190300, 2023). "However, The KM plot showed higher expression level of WT1 predicted worse overall survival time in thyroid cancer patients carrying BRAF mutation." (PMID 35123502, 2022). "One of the aggressive tumors, thyroid cancer, was also developed by the mutation in the BRAF gene." (PMID 36267655, 2022). "A significant contribution to the definition of the molecular profile was offered in 2014 by the Thyroid Cancer Genome Atlas assessing that PTCs are either a BRAF V600E or a RAS-driven tumor and that these mutations are able to activate the mitogenic-activated protein kinase (MAPK) pathway." (PMID 35634500, 2022). "The BRAF gene mutations have a particularly high frequency in thyroid cancer and LCH." (PMID 36246871, 2022). "The diagnostic and prognostic value of BRAF mutation in thyroid cancer has been well documented." (PMID 35402238, 2022). "As a highly effective risk-predicting and molecular marker for PTC, genetic testing for BRAF V600E mutation combined with FNA may improve the diagnostic accuracy of thyroid cancer and help surgeons to develop more individualized treatment plans." (PMID 36160023, 2022). "Furthermore, in a study of 138 cases including additional cases, the BRAF V600E point mutation was observed in 69.6% of cases, suggesting that it was different from the gene mutation in the thyroid cancer that occurred in Chernobyl." (PMID 36464297, 2022). "Modulation of the highly activated cytokine–cytokine receptor interaction pathway may offer new therapeutic options to overcome dabrafenib-induced resistance in BRAF-mutated thyroid cancer." (PMID 35515000, 2022). "Most of the current studies focus on the relationship between BRAF gene mutations and thyroid cancer, as well as factors related to prognosis, such as the relationship between BRAF mutations and thyroid cancer tumor invasion outside the perineum, lymph node metastasis, and pathological staging." (PMID 36160023, 2022). "In fact, the BRAF V600E allele is an oncogene for thyroid carcinoma." (PMID 35356255, 2022). "Previous studies have confirmed that non-BRAF genes were more common in other subtype thyroid carcinoma patients, which may have higher diagnostic value." (PMID 35992139, 2022). "In BRAF-mutated thyroid cancer, where single-agent inhibition of BRAFV600E signaling displays only modest anti-tumor effects, it was shown that autophagy was induced upon BRAFi as an adaptive response through endoplasmic reticulum (ER) stress in a MAPK signaling pathway-independent manner." (PMID 34298710, 2021). "Other molecular mechanisms may be involved in the genesis of thyroid cancers, such as a multicomponent signaling system involving fibroblast growth factor receptor, mutated BRAF signaling, and other communication pathways." (PMID 34234745, 2021). "Different tumour suppressor gene methylation and BRAF gene mutation in thyroid cancer." (PMID 34923978, 2021). "The second study describes four BRAFV600E-mutated thyroid cancer patients with disease progression during BRAF or BRAF/MEK inhibitor treatment and acquisition of secondary mutations in RAS genes (KRASG12V in two patients, and NRASQ61K and NRASG13D in the others)." (PMID 34072194, 2021).
thyroid cancer (continued). "Taken together, administration of a BRAF/MEK inhibitor not only increases RAI delivery to target lesions but also may contribute to increasing radiosensitivity to augment 131I therapeutic efficacy in thyroid cancer carrying RAS or BRAF mutations." (PMID 33977289, 2021). "The current study only included BRAF (V600E) mutations; however, a host of additional driver mutations including point mutations, copy number variations, and translocations have been identified in thyroid cancer." (PMID 34475951, 2021). "Interestingly, recent evidence indicated that the occurrence of secondary RAS mutations is involved in resistance to BRAF inhibitors in thyroid cancer." (PMID 34208446, 2021). "In addition, TSH stimulation, along with combination treatment with BRAF inhibitor and histone deacetylase (HDAC) inhibitor, maximized the synergistic effects of restoring thyroid-specific gene expression and RAI uptake in BRAF-mutated thyroid cancer." (PMID 33995657, 2021). "Thus, BRAF kinase inhibitors are expected to be effective against the BRAF mutated iodine-refractory thyroid cancers." (PMID 34944814, 2021). "For example, newly acquired secondary RAS mutations have been found in thyroid cancer patients treated with BRAF inhibitors and may act as an escape mechanism." (PMID 34335481, 2021). "The prevalence of BRAF mutation was higher than that in other types of thyroid cancers." (PMID 33672707, 2021). "Several studies have reported that the BRAF T1799A mutation may be involved in thyroid carcinoma and that the most mutated locus for this gene lies in exon 15 T1799A." (PMID 34934597, 2021). "We demonstrated that the diagnostic panel including the analysis of microRNA and mRNA expression, the V600E mutation in the BRAF gene, and mitochondrial-to-nuclear DNA ratio enables accurate identification of parathyroid and several types of thyroid carcinomas." (PMID 33440616, 2021). "However, thyroid cancer with dual mutations of RAS with BRAF V600E or TERT was associated with worse clinicopathologic outcomes." (PMID 32393293, 2020). "Additional biomarkers including NRAS and TERT promoter mutations are acknowledged to have a potential clinical significance in thyroid cancer and could be applied in synergy with BRAF mutation." (PMID 33247684, 2020). "Interestingly, a link between HIF-1α and BRAF mutations, which are a prevalent and well-known poor prognostic factor in papillary thyroid cancer, was suggested in thyroid cancer." (PMID 32847004, 2020). "Therefore, we aimed to develop a 7-gene mutation panel for FNA specimens and to test its diagnostic performance in the Korean population, where BRAF V600E is the most prevalent mutation in thyroid cancer." (PMID 32781560, 2020). "Thus, evaluation of the effects of HIF-1α inhibition in the mutant BRAF thyroid cancer cell line (BCPAP) would have a significant clinical implication in terms of the high BRAF mutation prevalence in thyroid cancer and its association with poor outcomes." (PMID 32847004, 2020).
thyroid cancer (continued). "The most common genetic alterations associated with MAPK and PI3K signaling pathways in thyroid cancer include mutations in BRAF, RAS, PTEN (Phosphatase and tensin homolog), AKT (Protein Kinase B), and PI3KCA (Phosphatidylinositol-4,5-Bisphosphate 3-Kinase Catalytic Subunit Alpha)." (PMID 32751138, 2020). "BRAF V600E (240 of 347 cases, 69%) was the most prevalent mutation in thyroid cancer." (PMID 32781560, 2020). "Furthermore, LDHA overexpression has been found in BRAF V600E-mutated thyroid cancer and inactivation of this protein can make cells more sensitive to radiation." (PMID 33382739, 2020). "Finally, a temporal trend in the changes in the thyroid cancer molecular profile characterized by an increasing prevalence of BRAF and RAS mutations supports the possibility that a true change in thyroid cancer biology is occurring." (PMID 32408629, 2020). "The occurrence of BRAF mutation in thyroid cancer is even more complex to analyze." (PMID 33260892, 2020). "Thus, traditional markers of thyroid cancer, like BRAF mutation or miRNA expression profile, can be evaluated in plasma." (PMID 32824820, 2020). "Thus, we aimed to develop a mutation panel to detect not only BRAF V600E, but also other common genetic alterations in thyroid cancer and to evaluate the diagnostic accuracy of the mutation panel for thyroid nodules in Korea." (PMID 32781560, 2020). "Few studies are currently available on the molecular profile of RAI-R thyroid cancers, either well differentiated, poorly differentiated or anaplastic, showing that they are enriched with BRAF mutations, whereas RAS mutations are more represented in RAI-A metastatic DTCs." (PMID 33198784, 2020). "More recently, the efficacy of BRAF inhibitors vemurafenib for advanced-stage BRAF exon 15 p.V600E-mutated thyroid cancer patients refractory to radioiodine treatment and dabrafenib for BRAF exon 15 p.V600E-mutated metastatic PTC patients has been demonstrated." (PMID 33260892, 2020). "Therefore, our data warrant the combination of BRAF V600E mutation testing to improve the diagnostic accuracy for the early detection of thyroid cancer." (PMID 32671901, 2020). "However, as previously reported, BRAF exon 15 p.V600E-mutated thyroid carcinomas are resistant to the radioiodine treatment approach." (PMID 33260892, 2020). "We speculate that PTCs in young people might be more genetically heterogeneous and genetic risk predisposition other than the BRAF V600E mutation contributes to the earlier onset of thyroid carcinoma in these patients." (PMID 32671901, 2020). "Clinically, it may suggest an aggressive, locally advanced thyroid cancer, an impression that may reflect on the selected surgical management, chemotherapy and BRAF mutation-targeting therapy to these patients." (PMID 30795755, 2019). "Although further studies are needed, these outcomes indicate that TERT is a new oncogene in thyroid cancer and promoter mutations may be promising in clinical management of thyroid cancer, especially in combination with BRAF V600E or RAS mutations." (PMID 31717449, 2019). "Previously, we described a reduction of oxidative phosphorylation in patients with thyroid cancer harboring the BRAF mutation, and we hypothesized that FGF21 was induced in the thyroid due to mitochondrial stress associated with thyroid tumorigenesis." (PMID 31408968, 2019). "Furthermore, induction of BRAF V600E mutation increased miR-17-92 cluster expression in thyroid cancer cells." (PMID 31835496, 2019). "We assumed that, in this context, information on BRAF mutation status in thyroid cancer tissue could be important in the determination of treatment strategy." (PMID 31810221, 2019). "Furthermore, in studies conducted on thyroid cancer patients who had the BRAF mutation, it was found that only 4% of patients experienced a complete response when exposed to this new therapy regimen." (PMID 31443155, 2019).